CISH (cytokine inducible SH2 containing protein)
Diseases named in the same sentence as CISH in open-access papers (continued):
Sharing a sentence is not in itself a finding about the gene and the disease.
tumor (continued). "A relevant human Phase-I/II clinical trial (NCT04426669, NCT03538613) targeting CISH−/− TILs in combination with ICB-therapy was proposed by Intima Bioscience, UK, until 2021𠄲2022 against wide range of tumor types and gastrointestinal cancer (Box-1)." (PMID 34571899, 2021). "Multiple lines of transcriptomic evidence in tumor-educated THP1 cells point to STAT3 pathway activation, including upregulation of canonical STAT3 targets (SOCS3, CISH, BCL3, JUNB, PIM1) and increased expression of STAT3-activating ligands (IL6, IL11, LIF, OSM) in response to TNBC contact." (PMID 41514627, 2025). "Gene-editing technologies (e.g., CRISPR/Cas9) have markedly augmented CAR-NK cell function, for instance, through knockout of inhibitory receptors (e.g., CISH, TGF-βR2) or metabolism-related genes (e.g., CD38), thereby improving both anti-tumor activity and adaptability to the TME." (PMID 41488873, 2025). "Moreover, knocking out the cytokine-inducible SH2-containing protein (CISH) gene leads to improved iNK cell proliferation and anti-tumor activity." (PMID 39533434, 2024). "Previously it was shown that targeting an intracellular TCR-signaling inhibiting protein CISH could improve TCR activation and tumor clearing in tumor bearing mice model." (PMID 38956389, 2024). "This study identified that the deletion of CISH yielded improved anti-tumour activity, and that acute myelogenous leukaemia (AML) could be treated more effectively with CISH-/- NK cells, and that these cells displayed increased persistence." (PMID 39676878, 2024). "Studies in CISH−/− mice show that NK cells without CISH have better tumor control and IL-15 sensitivity, especially in lung metastasis models." (PMID 39796666, 2024). "In vivo, the CISH KO in T-cells increased PD1 expression and the adoptive transfer of Cish-KO T-cells synergistically combined with PD1 antibody blockade resulting in durable tumor regression and survival in a preclinical animal model." (PMID 35884417, 2022). "A promising approach is the deletion of the CISH gene, coding for the negative regulator of IL-15 signaling CIS, which leads to improved NK cell metabolic profile, increased in vivo persistence and anti-tumor function of NK cells." (PMID 36348457, 2022). "Knocking out the CISH gene deletes the cytokine-inducible Src homology 2-containing (CIS) protein, a negative regulator of IL-15 signaling, which increases the cell’s metabolic activity and subsequent anti-tumor activity." (PMID 35565395, 2022). "Deletion of CISH in iPSC-derived NK or cord blood-derived NK resulted in increased JAK/STAT signalling and mTORC1 signalling leading to increasing NK cell metabolic fitness that directly contributed to improved anti-tumour responses." (PMID 34090499, 2021). "However, the CISH KO led to increased PD1 expression, whose adoptive transfer synergises with PD1 blockade, with durable tumor regression and survival benefits in the preclinical animal model." (PMID 34188916, 2021). "Interestingly, depletion of CISH (CRISPR/Cas9) in TILs significantly improved neoantigen recognition, TCR avidity, T-cell activation/expansion and tumor cytolysis, resulting in rapid-control over tumorigenesis." (PMID 34571899, 2021). "(iii) More relevantly, CISH has been shown in maintaining T-cell homeostasis via Mettl3-mediated methylation mechanism and (iv) The m6A-reader protein ‘YTHDF2’ is involved in controlling NK cell-mediated anti-tumour immunity." (PMID 34207299, 2021). "However, deletion of CISH in CD8+ T cells increased their proliferation and activity, including their cytotoxic anti-tumor capabilities." (PMID 34604264, 2021). "Tnfaip3 and CISH are important for host defense against infectious diseases and involved in negative feedback regulation of the tumor promoting effects." (PMID 25993608, 2015).
tumor (continued). "Based on baseline tumor samples, we observed that Cytokine-Inducible SH2-Containing Protein (CISH) exhibited higher expression in responsive tumor samples compared to non-responsive samples at baseline (10 responsive samples vs 7 non-responsive samples, p = 0.007)." (PMID 37537219, 2023). "Interestingly, some of them function as tumor suppressors (e.g. BCL2L11, MXD1, WWOX, BNIP3L, and DMTF1) or are candidate tumor suppressors having anti-proliferative properties and DNA repair abilities (e.g. LRRC2, RPA4, PPP6R1, SPEN, RAP1GAP and CISH) (see discussion section)." (PMID 26918450, 2016).
cancer (78 papers, 2003 to 2026). A tumor composed of atypical neoplastic, often pleomorphic cells that invade other tissues. "IL11, PTPN6 and CISH were significantly associated with survival outcomes in patients from 9 cancer cohorts." (PMID 31684858, 2019). "The genes associated with cancer Hallmarks were GNAI2, RHOA, MAPKAPK3, HYAL1, and CISH, while the most connected were RHOA, MST1R, and ATRIP." (PMID 40028213, 2025). "The authors concluded that the genetic disruption of CISH function offers a novel therapeutic approach to cancer, due to the negative regulation that CISH exerts on human T cell function." (PMID 39676878, 2024). "The results indicated that the promoter methylation levels of SOCS1 (p– = 7.379E‐07), SOCS3 (p = 4.534E‐10), SOCS5 (p = 1E‐12), SOCS6 (p = 5.534E‐11), and CISH (2.273E‐05) were lower in cancer tissues than in normal tissues." (PMID 39307915, 2024). "During the last few years, very few results have been published regarding expression of SOCS proteins, including CISH, in human cancers." (PMID 35884417, 2022). "Expression was heterogeneous through cancer samples, and as compared to normal breast expression, 44% of TNBCs were defined as “CISH-up” and 56% as “CISH-down”." (PMID 35884417, 2022). "One such internal regulator, the cytokine-inducible SH2-containing protein (CISH), has been knocked out using the CRISPR-Cas9 system and has been demonstrated to enhance reactivity towards cancer antigens in TIL therapy." (PMID 37190012, 2023). "In OSCC, miR-944 can target and inhibit the expression level of CISH, promote the activation of the Jak/STAT signaling pathway, and then promote the occurrence of inflammation and the invasion and migration of cancer cells." (PMID 36077769, 2022).
infection (43 papers, 2007 to 2026). The state of being infected such as from the introduction of a foreign agent such as serum, vaccine, antigenic substance or organism. "Nicotine (α7nAChR agonist) aggravated E. coli-induced BBB injuries, while MLA and MEM (α7nAChR antagonist) exhibited protective effects by regulating the α7nAChR/CISH/JAK2/STAT5 signaling pathways during infection." (PMID 36289622, 2022). "Furthermore, they discovered via gene silencing experiments that CISH impairs the proliferation of DC precursor cells initially, and instead triggers their differentiation into type 1 polarized DCs, which are essential for the innate immune response in pathogen infection." (PMID 39676878, 2024). "CISH protein was proven to negatively regulate the JAK2–STAT5 pathway and improve the tight junction destruction of HBMECs upon E. coli E44 infection." (PMID 36289622, 2022). "Additionally, five genes (CCL26, MIR8485, ULBP1, CCL13, CISH) and one unannotated gene (ENSG00000289505) were downregulated in the transwell relative to the other infection groups." (PMID 40630957, 2025). "Five hours after infection with Mtb, human macrophages silenced for STAT5 (siSTAT5) failed to induce CISH mRNA production, thus indicating that STAT5 acts as a transcriptional regulator of CISH in macrophages." (PMID 28954234, 2017). "However, this depletion of CISH did not alter the outcome of infection, with both CISH-/- and wild-type mice displaying similar parasitic load and cytokine responses." (PMID 39676878, 2024). "Besides, infection of macrophages with MTB leads to the secretion of granulocyte-macrophage colony-stimulating factor, triggering the expression of cytokine-inducible SH2-containing protein (CISH) through mediation by STAT5." (PMID 30650615, 2019).
infectious disease (18 papers, 2012 to 2026). A disorder directly resulting from the presence and activity of a microbial, viral, or parasitic agent in humans. "CISH is involved in the IL-2 signaling pathway, and it is reportedly associated with infectious diseases." (PMID 35453806, 2022). "Previous studies identified association of CISH promoter region single nucleotide polymorphisms (SNPs) with susceptibility to infectious diseases." (PMID 29411179, 2018). "Further studies are needed to address the question, how CISH variants mechanistically carry out their role during allergic, malignant, and infectious diseases." (PMID 29411179, 2018). "In this respect, increased susceptibility in individuals to various infectious diseases was linked to genetic polymorphisms in CISH." (PMID 28954234, 2017). "An association between multiple CISH polymorphisms and susceptibility to infectious diseases has been reported." (PMID 24964072, 2014). "So far, only three articles reported the relationship between CISH polymorphisms and infectious diseases." (PMID 24632804, 2014). "Cytokine-inducible Src homology 2(SH2) domain protein (CISH) gene was first associated with common infectious diseases in 2010." (PMID 24632804, 2014). "Another analysis, performed in Khor's study, found that the position −292 of the CISH promoter was the most highly associated, increasing the overall risk of infectious disease by at least 18% among persons carrying this variant allele." (PMID 25255143, 2014). "CISH has been implicated in the susceptibility of humans to a variety of infectious diseases." (PMID 37628937, 2023). "A previous study has found that the susceptibility to some infectious diseases is associated with a CISH polymorphism which indeed may affect the capacity of T cells to respond to inflammation caused by a pathogen, e.g. MTB." (PMID 24632804, 2014). "Our analysis further delineated peripheral transcripts, including the infectious disease susceptibility gene CISH, encoding cytokine inducible SH2-containing protein, and EBI3, encoding Epstein-Barr virus induced 3, putatively modulated by TNFα signaling." (PMID 24236088, 2013). "The variation in CISH results in the change of human sensitivity to infectious disease." (PMID 33519913, 2020). "Our results do not suggest a role of CISH SNPs in the susceptibility to T1D, whereas other reports showed an association with susceptibility to infectious diseases." (PMID 29411179, 2018).
bacterial infection (7 papers, 2011 to 2025). "In this study, the CISH protein was first proven to be mediated by α7nAChR in HBMECs under bacterial infection." (PMID 36289622, 2022). "CISH is known to control cytokine signals in phagosomes during bacterial infection." (PMID 40630957, 2025). "However, only the expression of CISH and SOCS1 and 3 was specifically upregulated by this bacterial infection." (PMID 22203897, 2011).
immune disorders (3 papers, 2021 to 2026). "Further investigation is warranted targeting CISH in DCs to check its immunotherapeutic competency in controlling Th1/Th2-associated immune disorders." (PMID 34571899, 2021).
inflammation (3 papers, 2017 to 2024). Aberrant reaction of the microcirculation characterized by movement of fluid and leukocytes from the blood into extravascular tissues. "CISH is present at specific expression levels in Treg cells in allergic-associated airway inflammation, implying the specific regulatory role of CISH in airway regional inflammation on the transcriptional level." (PMID 33519902, 2020).
CISH also shares sentences with these, for which no sentence is quoted: Insulin resistance (29 papers); autoimmune disease (12); malaria (9); prostate carcinoma (8); type 2 diabetes (8); Autoimmunity (7); lupus (6); bacteremia (5); hematological malignancies (5); rheumatoid arthritis (5); Arthritis (4); colitis (4); gastric cancer (4); lung cancer (4); psoriasis (4); uveitis (4); Allergy (3); atherosclerosis (3); atopic dermatitis (3); diabetic nephropathy (3); Graves disease (3); head and neck squamous cell carcinoma (3); Hyperglycemia (3); liver diseases (3); lung adenocarcinoma (3); multiple myeloma (3); multiple sclerosis (3); pancreatic cancer (3); periodontitis (3); ZIKV infection (3).
A further 99 diseases each share a sentence with CISH in 2 papers or fewer.